VWF (von Willebrand factor)
Diseases named in the same sentence as VWF in open-access papers (continued):
Sharing a sentence is not in itself a finding about the gene and the disease.
cancer (continued). "A vWF:Ag level above the 75th percentile was associated with a 3.8-fold increased risk of developing DVT, and an ADAMTS-13 level below the 25th percentile was associated with an approximately 2.7-fold increased risk of developing DVT in cancer patients after chemotherapy." (PMID 33292287, 2020). "We hypothesize that cancer cells that do not express VWF may be susceptible to the pro-apoptotic effect of exogenously applied VWF." (PMID 28035064, 2017). "However, in experiments in which anti-VWF antibodies were introduced in mice, these antibodies will exert their effect not only on VWF from endothelial and megakaryocytes, but also on the subpopulation of cancer cells that express VWF." (PMID 28035064, 2017). "A significantly higher number of VWF expressing cancer cells (NSsiRNA treated cells) transmigrated through the endothelial barrier compared to cells in which VWF was knocked down by VWFsiRNA treatment, demonstrating that VWF expression enhances transmigration of cancer cells." (PMID 28035064, 2017). "Thus, interfering with VWF function in VWF positive cancer cells may be the mechanism by which the metastatic process was affected in experiments that involved anti-VWF antibody." (PMID 28035064, 2017). "Furthermore higher VWF levels were detected in cancers with distant metastasis." (PMID 28035064, 2017). "A particular study examined the relationship between the Von Willebrand factor (VWF), cancer metastasis, and LMWH treatment." (PMID 40723905, 2025). "In cancer patients, a significant reduction in ADAMTS13 levels and a corresponding increase in VWF levels is observed." (PMID 39201740, 2024). "As for the DNA methylation, the cancers and the corresponding genes with hypermethylation were as follows: BRCA: VWF and ITGB3; COAD: QKI, DUSP9, and CNKSR2; KIRC: CNKSR1; PRAD: VWF, LMNA, and ITGB3; UCEC: ITGB3 and APBBAIP." (PMID 38217548, 2024). "Therefore, tethered VWF may play an important role in cancer metastasis by providing a “bridge” for cancer cell adhesion to EC directly through interacting with cancer cells or indirectly through recruiting platelets to EC and facilitating cancer cell adherence to platelets." (PMID 39282473, 2024). "Through this analysis, we identified eight major cell types, namely B cell (CD79A), cancer cell (KRT5), cycling cell (MKI67), endothelial cell (VWF), fibroblast (COL1A1), mast cell (KIT), monocyte/macrophage (CD14) and T cell (CD3D)." (PMID 38279519, 2024). "Von Willebrand factor (VWF), which plays a vital part in platelet adhesion along the endothelium, is involved in cancer metastasis and inflammation." (PMID 37214475, 2023). "No changes were detected in the plasma sE-sel, sICAM-1, vWF, and PAI-1, while tPA-1 concentration in the plasma was decreased by dabigatran treatment 24 h after i.v. injection of cancer cells." (PMID 35295330, 2022). "Another emerging concept is utilizing VWF and ADAMTS13 as predictive and prognostic biomarkers of cancer, given their altered levels in certain malignancies, as discussed in the previous section." (PMID 35327035, 2022). "A better understanding of the role that VWF and ADAMTS13 play in the promotion and inhibition of cancer and its metastasis will help to direct further translational studies to aid with the development of novel cancer prognostic tools and treatment modalities." (PMID 35327035, 2022). "A better understanding of the role VWF and ADAMTS13 play in the promotion and inhibition of cancer and its metastasis will help direct further translational studies to aid with the development of novel cancer prognostic tools and treatment modalities." (PMID 35327035, 2022). "The best-known angiogenic regulators in cancer are vascular endothelial growth factor A (VEGF-A), von Willebrand factor (VWF), and thrombospondin-1 (TSP-1)." (PMID 33809480, 2021).
cancer (continued). "With structural similarity to von Willebrand factor (vWF), MUC2 can also bind to collagen or other connective tissue components, making cancer cells lose permeability to resist chemotherapy." (PMID 34300195, 2021). "Notably, a significant rise in the plasma levels of VWF has been demonstrated in patients with malignant disease compared to benign conditions and healthy controls (p<0.005), with an even greater increase seen in patients with disseminated disease compared to early stage cancer (p<0.0001)." (PMID 33571850, 2021). "This increase in energy supply contributes to metastasis and is also facilitated by the stimulation of EMT, the invasion of cancer cells (BHLHE41), the development of acidosis (CA9), and an improvement in angiogenesis (VWF)." (PMID 34046336, 2021). "The principal strength of our study, however, lies in the large number of diverse cancer patients studied for ADAMTS‐13 and VWF and in its long follow‐up period." (PMID 31294335, 2019). "The aim of this investigation was to study the potential predictive value of ADAMTS‐13, VWF and their interrelationship for development of VTE in cancer patients and the correlation of values with survival probability in a large patient cohort." (PMID 31294335, 2019). "However, how vWF regulates cancer development and metastasis remains unknown." (PMID 29362409, 2018). "We showed that fibrinogen, interleukin-6, factor VIII, D-dimers, VWF, free TFPI and extracellular DNA were higher in cancer patients than in both CP and IPMN patients." (PMID 29899870, 2018). "In conclusion, many biomarkers including factor VIII, D-dimers, VWF, free-TFPI and MV-TF activity are related to cancer process and elevated levels of D-dimers, MV-FT activity and CA 19-9 are risk factors for VTE in PDAC." (PMID 29899870, 2018). "Further investigation is needed to study the angiogenic role and prognostic function of vWF in LAC angiogenesis and identify secreted paracrine factors directly responsible for modulating endothelial cell gene expression in cancer." (PMID 29299165, 2017). "Indeed, in the advanced stage of cancer progression (6th week after cancer cell inoculation), the impairment of NO-dependent response in the aorta was associated with the upregulation of vascular COX-2-derived PGI2 and increased expression of von Willebrand factor, vWF." (PMID 26935932, 2016). "In this study of retrieved clots from patients with LVO stroke, we found that clots from patients with concomitant active cancer displayed a distinct pattern compared to patients without cancer, with higher expression of vWF and H3Cit." (PMID 39760182, 2025). "VWF is the natural carrier for FVIII, which was found to be expressed and secreted by cancer cells." (PMID 39282473, 2024). "Surface immobilized VWF but not free VWF in solution can interact with integrin ανβ3 on the surface of EC or cancer cells under static conditions." (PMID 39282473, 2024). "In this study, no prognostic value was observed for VWF rs1063856, which aligns with the current gap in research regarding the role of this SNP in predicting cancer progression or patient outcomes." (PMID 39768338, 2024). "Therefore, we were not able to compare perioperative vWF activity between patients undergoing cancer versus non-cancer surgery, which might have helped to underline the high risk of postoperative thromboembolic events in patients having cancer surgery." (PMID 36769870, 2023). "Similarly, fibroblast-like cancer cells (C10) and endothelial cell-like cancer cells (C11) were identified based on the specific expression of fibroblast markers (DCN, COL1A2 and COL6A3) and endothelial cell markers (PCAT19, VWF and PLVAP)." (PMID 36451812, 2022). "On the other hand, VWF-expressing cancer cells should continue to metastasize in VWF knockout mice as they have no disadvantage in the absence of plasmatic VWF." (PMID 34572000, 2021).
cancer (continued). "As controls, we used mAb to lymphocyte function–associated antigen 1 (LFA-1)/CD11a/CD18, an isotype-matched anti-vWF mAb that does not bind to lymphocytes or cancer cells, and/or mouse IgG." (PMID 33497367, 2021). "Recent research has led to the discovery of additional non-haemostatic functions of VWF, including smooth muscle cell proliferation, immune response, angiogenesis [32,] and cancer metastasis." (PMID 33571850, 2021). "The results showed that there were 9 active components acting on key targets such as VEGFA, VWF, IL6, TNF, NFKB1, respectively, as well as regulating signaling pathways such as AGE-RAGE, FA, Toll-like receptor, PI3K/Akt, NF-κB, apoptosis and cancer signaling pathways." (PMID 33424592, 2020). "The vWF:Ag/ADAMTS-13 ratio was significantly higher in cancer patients with DVT than in those without (+ 4.12 vs. + 1.40, p = 0.001)." (PMID 33292287, 2020). "VWF remained an independent predictor of VTE occurrence in cancer patients even after adjustment for patient‐ and cancer‐related factors in the first multivariable model or adjustment for previously validated biomarkers of cancer‐associated VTE3 in the second model." (PMID 31294335, 2019). "A stage‐dependent increase in VWF and/or respective decrease in ADAMTS‐13 could indirectly imply the correlation with worse survival of cancer patients." (PMID 31294335, 2019). "These antibodies exhibited inhibitory potential on cancer metastasis by blocking the vWF-GPIbα axis without affecting platelet activation and hemostatic function." (PMID 30223883, 2018). "This hypothesis was tested in a mouse model in which NOD/SCID mice were infused with vWF-overexpressing BGC823 cells and monitored for blood-borne cancer grafting." (PMID 29362409, 2018). "To test the hypothesis that these vWF-mediated interactions enhance cancer metastasis, we measured the pulmonary grafting of BGC823 cells that had either a basal or an enhanced expression of vWF." (PMID 29362409, 2018). "Acquiring VWF expression by cancer cells of a non-endothelial/megakaryocyte origin suggests an alteration in the gene regulatory mechanisms that should otherwise inhibit VWF expression in these cells." (PMID 28035064, 2017). "Terraube and collaborators showed that VWF plays a protective role against cancer cell dissemination and absence of VWF leads to increased metastatic potential." (PMID 25846632, 2015). "One study analyzed the multimeric state of vWF and ADAMTS13 metalloproteinase activity on vWF in a wide range of cancers to understand the role of vWF and ADAMTS13 in dissemination and invasiveness of cancer." (PMID 24213506, 2012). "Moreover, in IDC paths #1 and #2, marker genes for endothelial cells (VWF and PECAM1), lymphocytes (CD4), macrophages (CD68), chemokines (CXCL12 and CCL5), and chemokine receptors (CXCR4) were expressed highly at the intermediate stages of cancer progression." (PMID 39965034, 2025). "Although numerous staining images are available, the interaction of vWF with cancer cells is not well described, suggesting that it may not be optimally expressed on the cell membrane in the presence of GC." (PMID 39456895, 2024). "Furthermore, the interaction of vWF with cancer cells has not been described, which precludes the assumption that this marker can be optimally expressed on the cell membrane in the presence of GC." (PMID 39456895, 2024). "The potential of endothelial damage and its resultant activation of vWF, within or without a known prothrombotic state such as cancer or autoimmune disease, to play a role in TTP brings to mind the question of whether it contributes to TTP." (PMID 38540234, 2024). "It has been shown that cancer cells, including those of non-endothelial origin, may acquire the ability to synthesize and release VWF, which then facilitates cancer progression and metastasis." (PMID 33800224, 2021). "Recently, vWF was detected also in cancer cells of non-endothelial origin including OS." (PMID 30279208, 2018).
cancer (continued). "However, the level of intracellular vWF was lower in these clonal cells than in primary cancer tissue from biopsy and surgery (data not shown)." (PMID 29362409, 2018). "Since VWF expression was long believed to be an exclusive property of these two cell types, the possibility that VWF may also be expressed in cancer cells of non-endothelial origin has been generally unexplored." (PMID 28035064, 2017). "Thus, demonstration of VWF expression in cancer cells, which are neither endothelial nor megakaryocytic in origin, presents a unique opportunity to determine how and why this endothelial specific gene is activated in some cancer cell types." (PMID 28035064, 2017). "Enhancement of affinity between [V4Q5]dDAVP and V2r present in cancer and endothelial cells could result in augmented cAMP production and PKA activation, angiostatin generation and VWF release, thus explaining the increased biological activity of the peptidic analogue." (PMID 25846632, 2015). "Conversely, immunopositivity for CD31 or von Willebrand factor would rule out carcinoma." (PMID 24520828, 2014). "However, the fact that GPIb- and GPII/IIIa-blocking antibodies demonstrated no impact on the formation of cancer cell-platelet aggregates in vitro suggests that molecules other than GPIb, GPIIb/IIIa, vWF and fibrinogen may be pivotal to their formation." (PMID 32191918, 2020). "However, there have been a few reports of VWF detection in cancer cells of non-endothelial origin." (PMID 28035064, 2017). "Results of the cohort of Pépin et al21 were similar, as cancer patients with VTE had mean ADAMTS‐13/VWF values of 0.36 (IQR 0.22‐0.49) and cancer patients without VTE had 0.44 (IQR 0.28‐0.57)." (PMID 31294335, 2019). "Considering that vWF may act as a key factor in resistance to metastasis and also as an inhibitor of angiogenesis, vWF may be a useful progrognostic marker; however, data from other studies have indicated that it may not be a general marker for all cancer types." (PMID 25886574, 2015).
cardiovascular disease (103 papers, 2005 to 2025). "D-dimer, coagulation factor VIII, and von Willebrand factor (VWF) levels have been associated with cardiovascular disease risk." (PMID 40725101, 2025). "In patients with DM, increased levels of VWF have been linked to a higher risk of complications such as cardiovascular diseases and DN." (PMID 38394492, 2024). "Elevated levels of VWF antigen (VWF:Ag) in blood plasma have often been associated with cardiovascular diseases." (PMID 39335520, 2024). "Among these, cardiovascular disease is the most frequent, where high shear stress in the bloodstream leads to excessive degradation of vWF multimers, resulting in the loss of large vWF multimers." (PMID 38822325, 2024). "In cardiovascular disease and stroke, elevated concentrations of VWF are linked to an increase in the severity of the disease." (PMID 38203218, 2023). "Population-based studies have shown that elevated vWF levels are a risk factor for thrombosis, especially in patients with previous cardiovascular disease and in the elderly." (PMID 35621950, 2022). "In this study, we used markers such as PAI-1, factor VII, fibrinogen, and vWF, for which high plasma levels or activities have been previously found to be associated with increased morbidity and mortality related to cardiovascular diseases." (PMID 35566668, 2022). "The combination of a low ADAMTS13 activity with a high concentration of VWF is likely to be prothrombotic with an increased risk of cardiovascular diseases and death." (PMID 34134634, 2021). "Elevated VWF-levels are directly associated with cardiovascular diseases (CD) of high-risk groups such as the elderly and diabetes patients." (PMID 33015097, 2020). "In this review, we discuss vWF involvement in complications of cardiovascular diseases and possible diagnostic and treatment approaches." (PMID 33096906, 2020). "The authors suggest that improvement in markers of endothelial functions (e.g. vWF) contributed to a decreased risk of cardiovascular disease in T2DM subjects." (PMID 31024058, 2019). "Low ADAMTS13 activity is associated with an increased risk of cardiovascular disease, which is generally attributed to its proteolytic effects on Von Willebrand factor (VWF)." (PMID 29615758, 2018). "Von Willebrand factor (VWF) is a minor component of plasma, but is implicated in acuteocclusive episodes in cardiovascular disease, and VWF levels are predictive of frequency andseverity of acute events." (PMID 26968213, 2016). "Elevated levels of VWF and D-Dimer are also associated with the development of cardiovascular disease." (PMID 26168189, 2015). "Adjustment for established cardiovascular disease risk factors moderately reduced the OR for VWF (Adjusted II and III)." (PMID 18194418, 2008). "Another systemic effect marker, fibrinogen, which is a risk factor for cardiovascular disease, contributes to plasma viscosity as does vWF, a pro-coagulant product of the endothelium." (PMID 15813961, 2005). "Consistent with other studies, the non-O blood group had a higher incidence and risk of developing cardiovascular diseases, which is related to the presence of high levels of von Willebrand factor (VWF), an important risk factor, which has been found to be the lowest in patients with O blood group." (PMID 35291516, 2022). "Therefore, we further tested the correlation between the relative levels of TIMP1, MMP2 and vWF (as assessed by slot blot) and several clinical/biochemical variables, and most common cardiovascular disease risk factors: age, BMI, or total cholesterol." (PMID 36362368, 2022). "In addition, high levels of coagulation parameters, such as factor VII (FVII), fibrinogen, von Willebrand factor (vWF), as well as low fibrinolytic activity have been associated with cardiovascular diseases." (PMID 33593303, 2021).